TNF (tumor necrosis factor)
Diseases named in the same sentence as TNF in open-access papers (continued):
Sharing a sentence is not in itself a finding about the gene and the disease.
Obesity (continued). "Numerous studies show that reducing obesity leads to lower lipid peroxidation and downregulation of genes in the tumour necrosis factor α/nuclear factor kappa-light-chain-enhancer of activated B cells (TNFα/NF-κB) signalling pathway." (PMID 40509530, 2025). "Therefore, potential effects of CCJ12 on various obesity-related risk factors (bodyweight, cholesterol, HDL, LDL, and triglycerides, leptin, adiponectin, sE-selectin, CRP, MCP-1 and TNF-alpha) were studied in rats fed a high fat diet." (PMID 40770283, 2025). "Several others, 8-OHdG, Ca2+, IL-6, IL-8, resistin, TNF-α, and AEA, have been identified as predictors, as they have previously been associated with an increased risk of developing obesity-related conditions such as insulin resistance, metabolic syndrome, or cardiovascular disease." (PMID 40153192, 2025). "Collectively, the dramatic suppression of MRC1 and the upregulation of TNF-α production induced by CTRP6 could aggravate the characteristic low-grade inflammation that persists chronically in obesity." (PMID 41159061, 2025). "GLP-1 receptor agonists, such as liraglutide, semaglutide, and exenatide, have been shown to decrease systemic inflammation by reducing circulating levels of inflammatory biomarkers, including hsCRP, TNF-α, and IL-6, in people with type 2 diabetes, obesity, and cardiovascular disease." (PMID 41511355, 2025). "Visceral adipose tissue is an active endocrine organ that secretes proinflammatory cytokines such as tumor necrosis factor-alpha (TNF-α), interleukin-6 (IL-6), and C-reactive protein (CRP), which contribute to systemic low-grade inflammation, a hallmark of obesity-related metabolic dysfunction." (PMID 40805992, 2025). "Obesity contributes to tumor progression not only through excess adiposity but also via a chronic inflammatory state characterized by elevated cytokines (e.g., IL-6, TNF-α) and adipokines such as leptin." (PMID 41008885, 2025). "TNF is considered one of the main factors driving low-grade systemic inflammation in obesity." (PMID 41153608, 2025). "TNF, produced by adipocytes and macrophages in adipose tissue, is elevated in obesity and diabetes." (PMID 40547917, 2025). "Animal evidence shows that obesity increases circulating TNF-α and VEGF levels." (PMID 41583457, 2025). "Therefore, LPS triggers systemic and local inflammation in the body that enhances liver injury and the degree of obesity by elevating pro‐inflammatory cytokine levels such as interleukin (IL)‐6, IL‐1, and tumor necrosis factor α (TNF‐α)." (PMID 40071130, 2025). "This is notably exacerbated in individuals with obesity, where excess adipose tissue acts as a potent source of pro-inflammatory cytokines such as IL-6, TNF-α, and leptin, which have been shown to enhance tumor cell proliferation, migration, and immune evasion." (PMID 41139205, 2025). "Similarly, omentin—secreted by visceral fat stromal cells—demonstrates anti-inflammatory properties, with inverse correlations reported between its circulating levels and markers such as CRP, IL-6, and TNF-α in individuals with obesity." (PMID 40868054, 2025). "Overall, individuals with overweight/obesity had higher levels of fibrinogen and TNFα." (PMID 40650919, 2025). "These macrophages secrete cytokines such as TNF-α, which play a role in obesity-induced IR." (PMID 40871683, 2025). "One possible explanation is that the adipose tissue itself leads to a systemic pro-inflammatory state by promoting the secretion and release of pro-inflammatory mediators such as IL-6, IL-1β, TNF-α, leptin, and MCP-1, so that obesity per se is a risk factor for the development of EDy." (PMID 40005022, 2025). "In obesity, adipose tissue chronic inflammation promotes the secretion of proinflammatory cytokines, such as tumor necrosis factor alpha (TNF-α), interleukin (IL)-1β, IL-6, IL-17, and interferon (IFN)-γ, which prolong the extension of chronic inflammation in adipose tissues." (PMID 40863244, 2025).
Obesity (continued). "Obesity induces a state of chronic low-grade inflammation characterized by elevated adipokines (e.g., leptin) and proinflammatory cytokines (e.g., TNF-α and IL-6), which promote airway hyperreactivity, increase mucosal permeability, and amplify IgE-mediated responses to occupational allergens." (PMID 41154935, 2025). "This was mainly attributed to decreased inflammation caused by reduced NF-κB activation upon obesity in the absence of TNF." (PMID 40961178, 2025). "Adipose tissue plays a crucial role in immune modulation, with dysfunctional adipose tissue in conditions like obesity or lipodystrophy releasing pro‐inflammatory cytokines (e.g., TNF‐α, IL‐6), which alter hepatic inflammation, a key factor in liver regeneration." (PMID 39980067, 2025). "In addition to circulating NK cells, obesity promotes their accumulation in visceral adipose tissue, where they produce TNF-α and polarize macrophages toward proinflammatory phenotypes." (PMID 41516046, 2025). "However, after adjusting for other comorbidities (obesity, T2D, and breast cancer), age, smoking, alcohol consumption, and ethnicity, MIP-1b/CCL4, TNFα, and VEGFα remained independently associated with HTN in our study cohort." (PMID 38541912, 2024). "In general, TNF-α levels may be elevated in obesity and CHD due to disturbances in inflammatory and immune processes, as well as metabolic dysfunction and heart damage." (PMID 38572445, 2024). "H. pylori may contribute to metabolic disorders and obesity by producing pro-inflammatory cytokines, such as tumor necrosis factor-α, interleukin (IL)-1, IL-6, and IL-8, which increase inflammatory responses and promote insulin resistance." (PMID 38971751, 2024). "We also found significantly lower DNA methylation levels of TNF-α in subjects with obesity and a WC ≥ 90 cm, TG concentrations ≥ 150 mg/dL, high blood pressure (systolic BP ≥ 130 mmHg or diastolic BP ≥ 85 mmHg), and FPG concentrations ≥ 110 mg/dL compared with those without MS." (PMID 38542788, 2024). "Conversely, factors such as chronic inflammation (as indicated by insulin resistance), obesity, smoking, elevated levels of tumor necrosis factor and C-reactive protein, or lower serum albumin levels have been linked with higher serum cystatin C levels, leading to lower eGFRcys according to mGFR." (PMID 39125705, 2024). "This inhibition was associated with reduced levels of pro-inflammatory cytokines, including interleukin 6 (Il6), tumor necrosis factor-alpha (Tnfα), and interleukin 1beta (Il1β), underscoring the potential of TC extract as a therapeutic intervention for mitigating obesity-induced inflammation." (PMID 39683572, 2024). "Inflammatory markers measured in obesity-related studies often include IL-6, TNF-α, and CRP." (PMID 38792936, 2024). "Additionally, the OR10J3 gene has been linked to tumor necrosis factor (TNF), which induces inflammation related to obesity." (PMID 39517154, 2024). "Aucubin could improve obesity-induced atherosclerosis by attenuating TNF-α-induced inflammatory responses." (PMID 38731500, 2024). "Increased TLR expression in mice with T1DM without associated obesity was accompanied by increased NF-κB, IL-6, IL-12, and TNF-α levels and decreased anti-inflammatory cytokine IL-10 levels." (PMID 39408723, 2024). "Regarding obesity, they reported some effects of adiponectin and leptin in cancer progression (the levels of these two adipokines are inversely and directly related to obesity) and they analyzed the role of a pro-inflammatory cytokine such as IL-6 and TNF-α in cancer development." (PMID 39410050, 2024). "Macrophages are considered to be a major source of proinflammatory mediators, and levels of proinflammatory adipokines including interleukin-6 (IL-6), monocyte chemotactic protein-1 (MCP-1), and tumor necrosis factor-α (TNF-α) are elevated in obesity and are connected with IR directly." (PMID 39080624, 2024).
Obesity (continued). "Moreover, ERK pathway overactivation in skeletal muscle can lead to inflammation through activation of TNF-α, IL-6, IL-1ß, and contribute to metabolic disorders such as type 2 diabetes and obesity." (PMID 38451972, 2024). "In addition, obesity and asthma showed a significant interaction effect on the plasma levels of IL-5, IL-10, IL-17A, IL-33, TNF-α, and leptin." (PMID 39902293, 2024). "In obesity, various cellular and molecular processes induce inflammation, especially in adipose tissues, which leads to the release of inflammatory mediators like tumor necrosis factor α (TNF-α), C-reactive protein (CRP), and interleukin 6 (IL-6)." (PMID 38725575, 2024). "Once calibrated, the BCIABM was used to simulate the B-cell response to repeat antigen stimuli during states of low, chronic background inflammation, implemented as low background levels of IL-6 and TNF-α often seen in patients with conditions such as diabetes, obesity, or advanced age." (PMID 38261584, 2024). "Obesity is characterized by an excessive accumulation of adipose tissue, which secretes a range of pro-inflammatory cytokines such as tumor necrosis factor-alpha (TNF-α) and interleukin-6 (IL-6)." (PMID 39588433, 2024). "As with TNFα, the plasma level of IL-6 increases with obesity and insulin resistance." (PMID 38257186, 2024). "Moreover, plasma EV counts of people with obesity positively correlated with body mass index and TNF expression in SAT, connecting increased EV secretion with AT expansion and inflammation." (PMID 38965596, 2024). "Treatment that reduces obesity symptoms could reduce epidermal thickness and eosinophil/mast cell infiltration, along with a reduction in IgE, IL-4, IL-6, TNF-α, and AD-like lesions." (PMID 39564133, 2024). "In addition, obesity promotes the transition of macrophages to the M1 phenotype, which secretes more pro-inflammatory cytokines (e.g., TNF-α, IL-6, and IL-1β)." (PMID 39831058, 2024). "Diacylglycerols are associated with a reduction in obesity and adverse cardiovascular events since they decrease the levels of C-reactive protein (CRP), tumor necrosis factor-alpha (TNF-α), fat accumulation, and platelet aggregation, which are considered CVD risk factors." (PMID 39408727, 2024). "Also, TNF-α was the most examined inflammatory factor (Pro-inflammatory) in obesity and NAFLD, and IL-6 was the most explored pro-inflammatory factor in diabetes." (PMID 38504163, 2024). "Furthermore, adiponectin has anti-inflammatory properties, and in obesity, the secretion of pro-inflammatory cytokines such as tumor necrosis factor-alpha (TNF-α) and interleukin-6 (IL-6) increases, while adiponectin levels decrease." (PMID 39728435, 2024). "Obesity was a chronic low-grade inflammatory state, which further exacerbated the inflammatory response induced by dyslipidemia by increasing circulating inflammatory factors, such as TNF-α and interleukin 6 (IL-6)." (PMID 39243068, 2024). "Furthermore, when prompted by TNF-α, such as during inflammation induced by obesity, adipocytes generate and release the chemoattractant molecule CCL5." (PMID 39606781, 2024). "Conditions such as obesity, type 2 diabetes, and metabolic syndrome frequently coexist with a chronic inflammatory state marked by elevated production of inflammatory adipokines, including interleukin-6 (IL-6) and tumor necrosis factor-alpha (TNF-α)." (PMID 38793119, 2024). "On the other hand, one research work revealed IL-6 as an independent predictor of type 2 diabetes, not TNF, while another demonstrated that hsCRP is a more sensitive marker associated with obesity than IL-6 and TNF." (PMID 38396488, 2024). "The inflammatory response observed in our study, characterized by increased intraepithelial lymphocyte infiltration and varying levels of the pro-inflammatory cytokines IL-6 and TNF-α, further underscores the role of chronic inflammation in obesity-related gut dysfunctions." (PMID 39684433, 2024).
Obesity (continued). "Oxidative stress and chronic inflammation may be increased with obesity, as well as the levels of IL-1β, IL-6 and TNF-α, which contribute to the development of lung injury." (PMID 38650653, 2024). "For instance, adipose tissue in obesity generates and releases an increased amount of pro-inflammatory adipokines, including tumor necrosis factor- alpha (TNF-α), interleukin-6 (IL-6), and leptin, which results in skin inflammation and is associated with psoriasis." (PMID 38550599, 2024). "Moreover, adipose tissue in older adults with obesity functions as a dynamic endocrine organ, secreting an array of hormones and pro-inflammatory cytokines, like TNF-a, IL-1a, IL-6, and CRP." (PMID 38668557, 2024). "Moreover, obesity changes the baseline levels of serum cytokines/adipocytokines IL-6, TNF-α, and CRP/hs-CRP." (PMID 39564133, 2024). "People with obesity experience chronic inflammation due to the endocrine function of adipocytes, which leads to a release of such pro-inflammatory cytokines as IL-6, IL-1β, and TNF-α." (PMID 39456224, 2024). "Indeed, the normal circulatory increase in cytokines, such as interleukin-6 (IL-6) and tumor necrosis factor-alpha (TNF-α), during the third trimester is exacerbated in women with overweight/obesity when compared to normal-weight women." (PMID 38671859, 2024). "Obesity leads to the accumulation of lipids in adipocytes and is responsible for triggering the release of inflammatory markers such as tumor necrosis factor-α (TNFα), interleukin-6 (IL-6), and C-reactive protein (CRP) and for insulin resistance." (PMID 39759127, 2024). "An important mention is that the pro-inflammatory phenotype M1 in obesity is different from the phenotype of M1 macrophages in acute inflammatory reactions, in that M1 ATMs express lower levels of pro-inflammatory CKs like TNF-α and IL-6 compared to the classical acute inflammatory M1 response." (PMID 39063610, 2024). "Of the 607 obesity-associated genes in our study, 120 have been found to be associated with adiposity in previous studies, such as the LEP gene encoding the adipokine leptin and several cytokines of the interleukin and tumor-necrosis-factor alpha families." (PMID 35953519, 2024). "However, an intervention study of an 8-week energy-restricted diet in individuals with obesity showed a strong association between the baseline TNF-α promoter methylation pattern and circulating TNF-α concentrations." (PMID 38542788, 2024). "Since obesity is characterized by a chronic inflammatory response, it has been demonstrated that low Nrg4 levels were negatively associated with inflammatory markers, such as hs-CRP, TNF-α, IL-6, and MCP-1 in conditions of MetS." (PMID 39162358, 2024). "Likewise, studies incorporating bariatric surgery and its role in obesity show a decrease in adiposity and in serum levels of IL-6, and TNF-α." (PMID 39184030, 2024). "Moreover, others have shown that RvD1 and RvD2 decreased TNFα and IL-6 and increased adiponectin in cultured adipocytes and adipose tissue explants using a mouse model of diet-induced obesity." (PMID 39337391, 2024). "ERα knockout (KO) mice have shown that a reduction in estrogen resulted in increased adipose tissue inflammation with the upregulation of pro-inflammatory genes, namely interleukins (IL-1β, IL-6) and tumor necrosis factor-alpha (TNFα); the development of obesity; and insulin resistance." (PMID 38791004, 2024). "Also, TME, insulin growth factor (IGF) signaling, tumor necrosis factor (TNF)-mediated pathways, xenobiotic metabolism, metabolic reprogramming, epigenetic mechanisms/hypermethylation, obesity and metaflammation all contribute to high race/ethnic disparities." (PMID 38612922, 2024). "Additionally, the systemic inflammatory markers, including levels of IL-1β, IL-1RA, IL-6, and TNF-α, were comparable between the overweight/obesity and healthy weight groups, suggesting similar inflammatory profiles regardless of weight status." (PMID 39201638, 2024).
Obesity (continued). "Moreover, the increase in intra-abdominal fat due to obesity excessively stimulates adipose tissue, leading to the secretion of inflammatory cytokines such as leptin, tumor necrosis factor-alpha (TNF-α), and interleukin (IL-6) by fat cells." (PMID 39011371, 2024). "Fluctuations in pro-inflammatory cytokine levels in HFD-fed zebrafish, particularly IL-6 and TNF-α, mirror findings in human obesity, where gastrointestinal inflammation plays a central role in the development of functional gastrointestinal disorders such as irritable bowel syndrome." (PMID 39684433, 2024). "Moreover, studies suggest a potential role for antibiotics, particularly vancomycin, in treating dysbiosis related to obesity by reducing TNF-α levels in mice and increasing insulin sensitivity in humans." (PMID 39596385, 2024). "Another possibility is that other inflammatory markers or signaling pathways may promote the observed association between obesity and hs-CRP levels, independently of TNF-α." (PMID 38550672, 2024). "If obesity persists, inflammatory cells infiltrate the adipose tissue of the body, resulting in increased secretion of cytokines, such as tumor necrosis factor-α (TNF-α)." (PMID 38257186, 2024). "An association between obesity and OA is related not only to the increased biomechanical overload, but also to the systemic effects of obesity, including low-grade inflammation with increased levels of proinflammatory cytokines (IL-1β, TNF-α, and IL-6) and reactive oxygen species, etc.." (PMID 38791302, 2024). "Additionally, mechanisms such as oxidative stress, inflammation (release of cytokines, such as TNF-α and IL-6), and apoptosis induced by aging and obesity impair testosterone synthesis, spermatogenesis, and sperm quality." (PMID 39765826, 2024). "The levels of TNF-α, IL-1β, and IL-6 are elevated in obesity." (PMID 39063610, 2024). "Moreover, the interaction strength between Il1bhigh monocyte subtypes and Pdgfrb+ stromal cell subtypes in the form of TNF − TNFrsf1α interaction was also enhanced subsequently to obesity, potentially contributing to ovarian fibrosis pathogenesis." (PMID 38956667, 2024). "The reduction in the mRNA levels of pro-inflammatory cytokines (TNF-α, IL-6, and IL-1β) signifies a robust anti-inflammatory effect of CME, offering a potential mechanism for its protective role against hepatic inflammation associated with obesity." (PMID 38999918, 2024). "Obesity is related to chronic inflammation and inflammatory makers such as IL-6 and tumor necrosis factor-α (TNF-α), which may induce an overreaction of the inflammatory process in response to infection." (PMID 38668323, 2024). "Obesity can induce a phenotypic shift of ATMs from M2 to M1, with pro-inflammatory cytokines such as TNF-α, interleukin (IL)-1, and IL-6, which are particularly secreted by M1 ATMs, exacerbating insulin resistance and contributing to local or systemic metabolic dysfunction." (PMID 39303983, 2024). "Furthermore, TNF-α is also involved in the pathogenesis of obesity and metabolic syndrome, affecting the body’s metabolic status by regulating inflammation in adipose tissue and insulin resistance." (PMID 38933362, 2024). "Indeed, obesity triggers increased circulating levels of the adipokine TNFα, while hepatic steatosis provokes local hypoxia." (PMID 38641009, 2024). "However, the current literature is inconclusive about the relationship between TNF-α and obesity or T2DM." (PMID 39519417, 2024). "For obesity, adipose tissues can release proinflammatory cytokines (e.g., tumor necrosis factor alpha, interleukin-1, interleukin-6, and adiponectin), which could activate the nitric oxide pathway in the brain and then cause headaches." (PMID 38378448, 2024). "Plasma TNFα and CCL2 levels were significantly elevated 6 weeks PS1 in Nx mice compared to sham mice, but remained in a low physiological range as observed in obesity-associated low-grade systemic inflammation." (PMID 38509307, 2024).